BRAF (B-Raf proto-oncogene, serine/threonine kinase)
Diseases named in the same sentence as BRAF in open-access papers (continued):
Sharing a sentence is not in itself a finding about the gene and the disease.
lung carcinoma (continued). "Such scenarios relate to biomarkers and testing in lung cancer, small cell lung cancer, EGFR mutations and targeted therapy in non-small cell lung cancer (NSCLC), early-stage NSCLC, KRAS/BRAF/MET and other genomic alterations in NSCLC, and immunotherapy in advanced NSCLC." (PMID 39237103, 2025). "Targeted therapy is an important method in the treatment of lung cancer, especially in the detection of common NSCLC mutations such as epidermal growth factor receptor (EGFR), rat sarcoma viral oncogene (KRAS), anaplastic lymphoma kinase (ALK), and BRAF genes." (PMID 39962757, 2025). "Known lung cancer genes (EGFR, KRAS G12C, ALK, MET, RET) were found in 33 patients; 11 had genes relevant to both lung and other cancers (ERBB2, BRAF V600, NTRK), and 37 had genes typically linked to other malignancies (NF1, PIK3CA, PALB2, FGFR2B, FBX7, RAD51)." (PMID 40244261, 2025). "More specifically, the use of targeted agents in patients without a BRAF mutation has been shown to have a very poor response rate to treatment of their disease and, extrapolating from lung cancer studies, a decrease in progression-free and overall survival." (PMID 39940799, 2025). "Subsequently, the patient underwent radical lung cancer resection and achieved pCR, suggesting that BRAF and MEK inhibitors may offer the potential for a curative approach in these patients." (PMID 41480531, 2025). "Secondary mutations in the EGFR driver gene are a primary cause of resistance to EGFR-TKIs 2, 3; in addition, other mutations including BRAF, PIK3CA, HER2 or c-MET amplifications, which were independent of EGFR pathway, account for 5-20% in EGFR-TKIs resistant lung cancer." (PMID 39744423, 2025). "ProKinO, an ontology tool for searching cancer kinome databases, has also identified various cancer-associated C-spine mutations, such as a valine to phenylalanine substitution in the receptor tyrosine kinase ErbB4 (V732F) and in the serine/threonine kinase BRAF (V471F) in lung carcinoma." (PMID 41207627, 2025). "Lastly, to validate the clinical relevance of our preclinical findings regarding exarafenib’s anti-tumor activity, we examined the clinical outcomes of patients with advanced BRAF-mutant lung cancer treated with exarafenib in the ongoing phase I/Ib clinical trial, KN-8701 (NCT04913285)." (PMID 41282105, 2025). "Based on assay design and coverage of key intronic regions of the genome, we were also able to detect a broad range of clinically relevant fusions, such as EML4::ALK, RET, and ROS1 rearrangements with diverse gene partners in lung carcinomas, BRAF::KIAA1549 and EGFRvIII alterations in gliomas." (PMID 39289779, 2024). "For lung cancer, we selected the drug Afatinib and the gene BRAF as our subjects of interest." (PMID 38754409, 2024). "These inhibitors bind to both protomers of the RAF dimer, stabilizing the αC-helix in the IN position (αC-helix IN/DFG-OUT RAF inhibitors or type 2), and are currently under preclinical and clinical evaluation in solid BRAF-mutant cancers, including lung cancer." (PMID 38731852, 2024). "For instance, both mutation and high amplification could be detected in EGFR, MET, and ERBB2 in lung cancer, as well as mutations in KRAS, BRAF, STK11, KEAP1 and many others." (PMID 39289779, 2024). "This case serves as a call for further research into the molecular underpinnings of BRAF-mutant lung carcinomas and highlights the need for clinical trials to explore novel therapeutic agents targeting specific molecular pathways in patients with non-V600E BRAF mutations." (PMID 39040442, 2024). "In 2011, the International Association for the Study of Lung Cancer, American Thoracic Society and European Respiratory Society introduced papillary subtype of lung adenocarcinoma coexisting with very high TTF-1 expression (90–100%) and 5% BRAF mutation." (PMID 39767631, 2024). "Mutations in BRAF and MEK are also observed in a subset of lung cancer patients." (PMID 39544928, 2024).
lung carcinoma (continued). "Patients with mutations such as KRAS, BRAF and c-MET may benefit from NA ICI-chemo based on the extrapolation of the benefit of immunotherapy in patients with advanced lung cancer who have these mutations." (PMID 38610980, 2024). "Molecular alterations such as EGFR mutations, ALK rearrangements, ROS1 rearrangements, RET rearrangements, NTRK fusions, MET mutations, KRAS mutations, BRAF V600E mutations, and HER2 mutations are the contributing factors that underlie the aggressiveness of lung cancer." (PMID 38474400, 2024). "In colorectal and lung cancers, due to their higher baseline RTK activity, the resulting RAS activity is sufficient to support the activation of class III BRAF mutants; therefore, only a minority of class III BRAF-mutation cases coexist with RAS/NF1 mutations." (PMID 39529955, 2024). "This case may provide an opportunity for clinicians to consider the order of administration of immunotherapy and molecular targeted therapy for BRAF V600E-positive lung cancer." (PMID 38429896, 2024). "Moreover, sensitivity to erastin-induced ferroptosis was also reduced in shRNA-mediated KRAS-silenced Calu-1 lung cancer cells, and inhibition of BRAF activity was also found to reduce sensitivity to erastin in BRAF-silenced A-673 cells." (PMID 37580745, 2023). "This budget may double in the case of NSCLC analysis, because lung carcinomas have to be additionally tested for EGFR, BRAF, KRAS, MET, and HER2 mutations as well as ALK, ROS1, and RET translocations." (PMID 37762506, 2023). "Sporadic examples of BRAF exon 12 in-frame deletions have also been reported in human myeloid neoplasms, lung carcinomas, colon carcinomas and prostatic carcinomas, in which they are mutually exclusive from V600E mutations, and also from mutations of RAS genes." (PMID 37079639, 2023). "In lung carcinomas, BRAF mutations are rare and have not been extensively investigated in the literature, with limited data on therapeutic options." (PMID 37999148, 2023). "In this regard, [89Zr]-anti-PD-1 (immuno-PET) may probably perform similarly well in other lung cancer subtypes for which immunotherapy has been approved in frontline treatment or as subsequent lines (KRAS or BRAF mutant lung tumors)." (PMID 37841258, 2023). "Among the detected alternations, the eight-major driver mutations of lung cancer (EGFR, ALK, ERBB2, MET, RET, ROS1, BRAF, and KRAS) could be found in 14 out of 17 (82.4%) patients using both surgical and CNB specimens." (PMID 36224661, 2022). "In treatment-naïve lung cancer, oncogenic driver mutations, such as epidermal growth factor receptor (EGFR), Kirsten rat sarcoma virus (KRAS), BRAF, anaplastic lymphoma kinase (ALK), and ROS1, typically occur as trunk mutations with little intratumoral heterogeneity." (PMID 35008406, 2022). "Moreover, lung cancer cells carrying ATM mutation and wild-type RAS and BRAF, such as EBC-1, display a strong dependency on MEK linked to the ATM heterozygous mutation." (PMID 35628590, 2022). "Thus, we sought to delve into this subset of lung cancer patients in an attempt to provide a real-life portrayal of the BRAF mutant population, particularly highlighting similarities and discrepancies between V600E and non-V600E groups." (PMID 35454926, 2022). "For example, the data from two large German lung cancer centers showed that patients with BRAF-mutated NSCLC had an inferior prognosis, which was not determined by the BRAF mutation functional class." (PMID 36230688, 2022). "Mutations in lung cancer driver genes (KRAS, EGFR, BRAF, ALK, ROS1, MET, RET, and ERBB2) in the high- and low-risk groups were shown on a waterfall plot, which demonstrated that the low-risk group (20%) harbored a higher EGFR mutation frequency than did the high-risk group (8%)." (PMID 36353226, 2022). "However, prevalence, clinical features and treatment outcomes of class 2 and 3 BRAF alterations in patients affected by lung cancer are still poorly studied." (PMID 35884534, 2022).
lung carcinoma (continued). "Twelve (18%) patients had KRAS mutation, two patients were EGFR mutation‐positive (3%), one patient had a BRAF mutation (2%) and no patient had lung cancer that was ALK mutation‐positive." (PMID 34196124, 2022). "In lung cancer, for example, YAP1 activation confers resistance to therapies targeted against common lung cancer oncogenes, such as anaplastic lymphoma kinase (ALK), BRAF or mutated epidermal growth factor receptor (EGFR) tyrosine kinase." (PMID 34685695, 2021). "The incidence of BRAF mutations in NSCLC is low, accounting for 0–3% of all cases of lung cancer." (PMID 33474634, 2021). "In this regard, lung cancer investigations revealed that smoking could increase the EGFR and its downstream elements, such as KRAS and BRAF mutations." (PMID 33127962, 2020). "In contrast to the results of TCGA4,5, we detected low mutational frequencies of STK11, NF1, and BRAF were detected in LUAD and low mutational frequency of KEAP1 in both LUAD and LUSC, indicating the special molecular characteristics of Chinese lung cancer patients." (PMID 33219256, 2020). "In addition, further researches about the role of mucins in lung cancer with different mutational background such as K-ras, EGFR, and BRAF are necessary to guide the combination therapy and overcome drug-resistance for lung cancer." (PMID 32807223, 2020). "The prognostic implication of these BRAF mutations has not been clearly established, but they tend to associate with poor survival in the early-stage but not advanced-stage lung cancer patients." (PMID 33037234, 2020). "A study on nonmelanoma patients with a BRAF mutation treated with vemurafenib found that the response rates of non‐small cell lung cancer and Erdheim‐Chester disease or Langerhans cell histiocytosis with a BRAF mutation were 42% and 43%, respectively." (PMID 32476297, 2020). "There are no reports of an abnormal distribution of BRAF mutations in young lung cancer patients in the literature." (PMID 31387567, 2019). "In lung cancer, to the best of our knowledge, only two studies provided in-depth evaluation of the clinical feasibility and diagnostic value of IHC with the VE1 antibody for the detection of the BRAF V600E mutation." (PMID 31234388, 2019). "Several examples include the v600E BRAF mutation, which predicts response to specific BRAF inhibitors, as well as high BRCA1 expression predicting resistance to neoadjuvant gemcitabine/cisplatin chemotherapy in lung cancer." (PMID 30352973, 2018). "Combinatorial strategies could be effective in overcoming TKI resistance in lung cancer and have already shown some promise, such as in BRAF-mutant NSCLC." (PMID 29973561, 2018). "While our study is the first report on sorafenib/AZ628 and selumetinib combination, there are already studies on non-V600 BRAF mutant lung cancer cell lines using the BRAF V600E mutant selective inhibitors dabrafenib or vemurafenib and the MEK inhibitor trametinib." (PMID 29739364, 2018). "Likewise, in on-going clinical trials testing MEK and BRAF inhibitors in KRAS- and BRAF-mutant lung cancer, responses have been reported in some patients." (PMID 28145866, 2017). "This suggests that ATM knockdown can affect the response to MEK inhibition in both the presence and absence of KRAS or BRAF mutations, both of which are common in lung cancer." (PMID 27922010, 2016). "Together these experiments demonstrate that ATM inactivation by shRNA knockdown or CRISPR/Cas9 knockout strongly sensitizes lung cancer cells to MEK inhibition even in the absence of KRAS or BRAF mutations." (PMID 27922010, 2016).
lung carcinoma (continued). "MRNAs of Hmga2 and BRAF could induce lung cancer progression and lymphoma formation respectively, which suggests these mRNAs may be a therapeutic targets for these malignant diseases." (PMID 26872371, 2016). "Although many molecular genetic studies have implicated certain genetic mutations in non-small cell lung cancer (NSCLC), including mutations in the EGFR, PIK3CA, BRAF, KRAS, and ALK genes, only a few studies have focused on the genetic events associated with salivary gland-type lung carcinomas." (PMID 26373952, 2015). "In conclusion, the present study determined BRAF amplification in lung cancer for the first time and demonstrated that BRAF copy number gain may be present in BRAF V600E cases." (PMID 25621040, 2015). "Cigarette and coal dust have been proven to be mutagenic factors of KRAS and BRAF in lung cancer." (PMID 25013473, 2014). "Clinical trials are ongoing in lung cancers carrying PIK3CA, BRAF or KRAS mutations." (PMID 24236184, 2013). "However, we did not detect an obvious correlation between mutational expression of EGFR, BRAF, PI3KI, or KRAS and sensitivity to AZD6244 or MK2206 in the lung cancer lines we tested." (PMID 21124782, 2010). "Therapeutic advances in treatment of lung cancer have included targeted therapies, which are available for patients with mutations in oncogenes such as ROS Proto-Oncogene 1 (ROS1), epidermal growth factor receptor (EGFR), anaplastic lymphoma kinase (ALK), and B-raf proto-oncogene (BRAF)." (PMID 41316207, 2025). "Research on targeted therapy for BRAF has focused on the V600E mutation, but class II and III BRAF mutations have also been found to be the driving mutations in lung adenocarcinoma, and the rate of non-BRAF V600E mutations can be as high as 50–80% in all BRAF mutant lung cancers." (PMID 38538919, 2024). "Notably, BRAF mutations demonstrated a significantly higher frequency in patients with lung cancer with IPF, accounting for 6 of 35 cases (17.1%), which is much higher than the known prevalence of 2–4% in the general lung cancer population." (PMID 38611005, 2024). "In a previous study conducted by the University of California Lung Cancer Consortium, 54.9% of patients had EGFR mutations, 32.9% of patients had KRAS mutations, 5.3% of patients had ALK fusions, and < 3% of patients had other mutations (HER2, MET, RET, ROS1, or BRAF-non-V600E)." (PMID 39009968, 2024). "Improved understanding of the biology of lung cancer has resulted in the development of new biomarker-directed therapies targeting molecular alterations (eg, EGFR mutations, ALK rearrangements, ROS1 rearrangements, and BRAF V600E mutations), which have prolonged survival of lung cancer patients." (PMID 33442422, 2021). "Additionally, mutations in the KRAS, BRAF, and PIK3CA genes have emerged as an important predictive marker of resistance to epidermal growth factor receptor (EGFR)-targeting monoclonal antibodies or tyrosine kinase inhibitors in colorectal and lung cancers." (PMID 33054840, 2020). "Therefore, elimination of BRAF restrains the growth of lung cancer cells." (PMID 33228740, 2020). "Thus, if the PIK3CA/BRAF prevalence in AEC is validated in a larger study, it would be reasonable to consider trials in which the AEC mutation spectrum is measured before and after treatment of lung cancer subjects bearing cancers that also have the mutation." (PMID 31711466, 2019). "Moreover, the clinical characteristics of patients with lung cancer carrying BRAF V600E mutation are not consistent across different studies." (PMID 31234388, 2019). "Because larger mutation screenings—including RAS, BRAF, MET (mutations, amplifications), ERBB2 (mutations, amplifications), ALK (mutations) and ROS (mutations)—were shown to be useful in the management of lung cancer patients, targeted NGS is progressively replacing single gene testing methods." (PMID 29890761, 2018).
lung carcinoma (continued). "Due to the small size of our patient cohort, we could not detect any significant clinical differences between BRAF mutated and other molecular subtypes of lung cancer or between different BRAF mutation types." (PMID 28947956, 2017). "In addition, LKB1 loss also was observed concurrently with KRAS oncogenic mutation promoting pancreatic tumorigenesis by suppression of P21-dependent growth arrest and with BRAF V600E inducing lung adenomas progression to lung carcinomas by overcoming senescence." (PMID 29371951, 2017). "Thus, our findings suggest that including ATM mutational status in lung cancer as a mechanistic biomarker for MEK inhibitors can improve patient stratification, potentially extending the applicability of these drugs beyond RAS and BRAF mutant tumours." (PMID 27922010, 2016). "Furthermore, some RAS and BRAF wild-type lung cancer cell lines display strong dependency on MEK." (PMID 27922010, 2016). "Despite the small numbers in these rare lung cancer subtypes, SNV calling using the OncoMap database revealed previously undescribed SNV in FGFR1, CDKN2A, RB1, JAK3, and CTNNB1 for the large-cell type, a BRAF mutation for carcinoid, and an AKT1 mutation for adenosquamous carcinoma." (PMID 26076459, 2015). "The fact that the molecular analysis of the brain metastases in our case confirmed a BRAF mutation in this tissue raises the question whether there could be also a correlation of the BRAF status with multiple and miliary organ metastasis as seen under EGRF mutations in lung cancer." (PMID 26187589, 2015). "Mutations in several oncogenes are well-characterized driver events in various cancers, e.g., mutations in KRAS G12 residue in pancreatic and lung cancer, BRAF V600 in melanoma, and the EGFR L858 in lung cancer." (PMID 41567248, 2026). "Discovery and drug development of new lung cancer‐related targets: EGFR, ALK, ROS1, RET, MET, BRAF inhibitors, etc." (PMID 40135802, 2025). "We extended the study to three lung cancer cell lines used in the co-IP experiments and assessed the effects of each RAF inhibitor on endogenous ARAF, BRAF, and CRAF kinase activity." (PMID 41282105, 2025). "In conclusion, our study showed that one twentieth of lung cancer patients diagnosed in Germany in 2016 received at least one EGFR, ALK, or BRAF inhibitor during follow‐up." (PMID 39693368, 2024). "In our study, 49 (12.5%) of the lung cancer patients treated with EGFR, ALK, or BRAF inhibitors were diagnosed at a non‐advanced stage." (PMID 39693368, 2024). "One twentieth of lung cancer patients diagnosed in 2016 in Germany received at least one EGFR, ALK, or BRAF inhibitor during follow‐up." (PMID 39693368, 2024). "The prevalence of driver oncogenic alterations in patients with lung cancer, particularly EGFR, BRAF, HER2 and ROS1, was significantly higher in high exposure areas." (PMID 36208308, 2022). "Sequentially, we evaluated the targetable variations detected ability in different samples, including EGFR, ALK, BRAF V600E, KRAS, MET ex14 skipping, RET, ROS1, ERBB2, which have high evidence in lung cancer." (PMID 36167530, 2022). "Latest results have shown that around 83% of the lung cancer patients included in the cohort study (n = 2.204) were tested for EGFR, ALK, ROS-1, PD-L1 and / or BRAF." (PMID 35765059, 2022). "EZH2 was also highly expressed in the lung cancer with positive KRAS expression, exhibiting a positive correlation, as well as with the expression of BRAF, especially in lung squamous cell carcinoma." (PMID 36195655, 2022). "Analysing public data sets revealed that gene expression of the PI3K‐MAPK downstream effectors, AKT2 and BRAF, positively correlated with USP28 in lung cancer cell lines and in various tumour entities." (PMID 35364627, 2022). "Genetic testing for advanced nonsmall cell lung cancer (NSCLC) includes EGFR, ALK, ROS1, BRAF, MET, HER-2, RET, NTRK1/2/3, PI3K, and PD-L1." (PMID 35368895, 2022).